TMOD2 (tropomodulin 2)
Description:
Blocks the elongation and depolymerization of the actin filaments at the pointed end. The Tmod/TM complex contributes to the formation of the short actin protofilament, which in turn defines the geometry of the membrane skeleton (By similarity).
Synonyms: N-Tmod; NTMOD
Tractability: PROTAC: its protein half-life has been measured.
Gene: Protein-coding gene on chromosome 15 (51,751,564 to 51,816,363, forward strand). Ensembl gene ENSG00000128872.
Subcellular location: Cytoplasm, cytoskeleton
Subcellular location (Human Protein Atlas): Nucleoli fibrillar center; Nucleoplasm
Pathways (Reactome):
Muscle contraction: Striated Muscle Contraction
Gene Ontology:
Molecular function: protein binding; actin binding; tropomyosin binding
Biological process: actin filament organization; muscle contraction; myofibril assembly; nervous system development; pointed-end actin filament capping
Cellular component: cytoskeleton; striated muscle thin filament
Genetic constraint (gnomAD): Loss-of-function variants: 20 observed, 36.62 expected, observed/expected ratio (o/e) 0.55, 90% interval 0.38 to 0.79. The upper end of that interval is the gene's LOEUF score, 0.79, which puts it in group 3 of 6, group 1 being the genes least tolerant of losing a copy. Missense variants: 367 observed, 414.28 expected, observed/expected ratio (o/e) 0.89, 90% interval 0.81 to 0.97. Synonymous variants: 120 observed, 149.12 expected, observed/expected ratio (o/e) 0.8, 90% interval 0.69 to 0.94.
Homologues: Orthologues: chimpanzee TMOD2 (99% identical), macaque TMOD2 (99% identical), pig TMOD2 (97% identical), mouse Tmod2 (95% identical), rabbit TMOD2 (94% identical), guinea pig TMOD2 (94% identical), rat Tmod2 (93% identical), tropical clawed frog tmod2 (75% identical), Caenorhabditis elegans unc-94 (35% identical), Drosophila melanogaster tmod (27% identical). Paralogues in human: TMOD3 (76% identical), TMOD1 (60% identical), TMOD4 (54% identical), LMOD2 (40% identical), LMOD1 (38% identical), LMOD3 (37% identical).
Diseases named in the same sentence as TMOD2 in open-access papers:
TMOD2 is named in the same sentence as 10 diseases in open-access papers, as found by Europe PMC text mining. Sharing a sentence is not in itself a finding about the gene and the disease. The quoted sentences say what the papers report.
neuroblastoma (3 papers, 2013 to 2023). Neuroblastoma (NB) is the most common solid, extracranial childhood tumor. "Our data clearly demonstrated extensively a positive and specific correlation between TMOD1 and TMOD2 expression levels and neuroblastoma; high expression levels of these two genes were associated with high survival probability and good prognosis of neuroblastoma patients’." (PMID 29930753, 2018). "We assessed the expression of TMOD1 and TMOD2 genes in 17 different datasets comprising different types of tumors and we added an additional neuroblastoma dataset as control." (PMID 29930753, 2018). "TMOD1 and TMOD2 were highly expressed in neuroblastoma, relative to other tumor types, suggesting an important role of these genes in the tumor homeostasis." (PMID 29930753, 2018). "TMOD2 high expression levels correlate with high survival probability and favorable disease outcome in neuroblastoma patients’, while TMOD3 up regulation is responsible for chemotherapeutic agents’ resistance in non-small cell lung carcinoma." (PMID 29930753, 2018). "TMOD2 is part of a 160 gene signatures predicting neuroblastoma outcome and of a 55 gene signature predicting neuroblastoma outcome in metastatic neuroblastoma lacking MYCN amplification." (PMID 29930753, 2018). "We found that TMODs expression varied among tumor types but the highest expression of TMOD1 and TMOD2 was observed in neuroblastoma tumors (Bonf p<0.01)." (PMID 29930753, 2018). "In N2a neuroblastoma cells (model system to study neuritogenesis), both Tmod1 and Tmod2 were expressed, but levels of Tmod1 increased drastically starting 24 hours after induction of neuritogenesis." (PMID 23638401, 2013). "It was shown that Tmod2 levels remain fairly constant in N2a neuroblastoma and PC12 cells." (PMID 37627302, 2023). "First, we evaluated the presence and the expression levels of TMOD1 and TMOD2 in SH-SY5Y and SK-N-SH neuroblastoma cells." (PMID 29930753, 2018). "Knockdown of Tmod2 in N2a neuroblastoma cells increased the percentage of cells with neurites (no change in number of neurites) and the length of neurites was increased 2-fold." (PMID 23638401, 2013).
glioblastoma (2 papers, 2022 to 2023). The most malignant astrocytic tumor (WHO grade IV). "According to the signature that included four genes (TMOD2, CACNG2, PLOD3, and TMSB10), glioblastoma patients were divided into high and low risk score groups." (PMID 35788194, 2022). "In glioblastoma, a study constructed a signature by four m7G-related genes (TMOD2, CACNG2, PLOD3, and TMSB10) and could predict the prognosis of glioblastoma patients." (PMID 36732869, 2023).
adenoma (1 paper, 2025). A neoplasm arising from the epithelium. "The involvement in immune microenvironment regulation and genomic stability maintenance further underscores TMOD2's multifaceted role in adenoma pathogenesis." (PMID 41378121, 2025). "Collectively, these findings validate the distinct expression patterns of TMOD2 and DOCK4 in colorectal carcinogenesis (from normal tissues to adenoma to cancer), and provide a molecular framework for understanding the role of the two genes in the pathogenesis of intestinal adenomas and carcinomas." (PMID 41378121, 2025).
cerebral malaria (1 paper, 2023). A sequestration of Plasmodium falciparum in the brain, which can cause coma and/or seizures. "A decrease in the expression of tropomodulin-2 was observed, and it suggests that the genes involved in coagulation play a crucial role in the coagulation cascade in cerebral malaria." (PMID 37048057, 2023).
idiopathic pulmonary fibrosis (1 paper, 2025). Idiopathic pulmonary fibrosis (IPF) is a nonneoplastic pulmonary disease that is characterized by the formation of scar tissue within the lungs in the absence of any known cause. "TMOD2 acts as a fibrogenic gene in idiopathic pulmonary fibrosis (IPF) and exhibits a shortened 3’UTR and increased protein expression levels." (PMID 41452853, 2025).
tumor (3 papers, 2018 to 2025). "Single-cell analysis revealed that TMOD2 exhibits broad expression across multiple cell types within the tumor microenvironment, with notable exclusion from mast cells, suggesting its fundamental role in maintaining cellular structural integrity across diverse cell populations." (PMID 41378121, 2025). "It is also reported that knockdown of E2F1 inhibited tumor cell proliferation and promoted apoptosis in castration-resistant prostate cancer (CRPC) by regulating TMOD2 and AIF1L expression." (PMID 35392496, 2022).
cancer (2 papers, 2022 to 2025). A tumor composed of atypical neoplastic, often pleomorphic cells that invade other tissues. "However, no studies demonstrated the role of ASXL3, TMOD2, and CEP85L in cancer." (PMID 35550610, 2022).
TMOD2 also shares sentences with these, for which no sentence is quoted: colorectal (1 paper); colorectal adenoma (1); neurodegenerative disease (1).